NAT10 (N-acetyltransferase 10)
Diseases named in the same sentence as NAT10 in open-access papers (continued):
Sharing a sentence is not in itself a finding about the gene and the disease.
liver cancer (12 papers, 2017 to 2025). An epithelial or non-epithelial malignant neoplasm that arises from the liver. "Our findings demonstrate that knockdown of NAT10 or inhibition of its activity using small molecules NAT10‐2023 effectively suppresses tumor formation in spontaneous liver cancer models while mitigating liver damage associated with tumor progression." (PMID 41476650, 2025). "Correlation analysis of the TCGA liver cancer database revealed a positive association between the expression levels of NAT10 and SMAD3." (PMID 41476650, 2025). "As a crucial regulatory factor, NAT10 has been implicated in major human diseases including liver cancer, breast cancer, gastric cancer, colorectal cancer, and myocardial infarction." (PMID 41476650, 2025). "In a 2018 study, statistical analysis of immunohistochemical staining revealed that the cytoplasmic and cell membrane localization of NAT10 in liver cancer tissues was associated with a poorer clinical prognosis than its nucleolar localization." (PMID 41316475, 2025). "Additionally, a recent study revealed that high NAT10 expression is associated with increased liver cancer risk and poor prognosis." (PMID 39764566, 2025). "In liver cancer, NAT10 directly upregulates the ac4C modification levels of HSP90AA1 mRNA, enhancing its stability and improving its antiapoptotic capacity against lenvatinib." (PMID 39764566, 2025). "Research shows that NAT10 is highly expressed in liver cancer, and higher expression correlates with shorter patient survival times." (PMID 39764566, 2025). "These insights significantly contribute to the understanding of liver cancer mechanisms and highlight the potential for novel therapeutic strategies targeting NAT10‐related pathways." (PMID 41476650, 2025). "In liver cancer, significant variations in NAT10 expression were observed between tumor and adjacent healthy tissues, suggesting its potential utility as a supplementary biomarker for the diagnosis of malignant tumors." (PMID 41316475, 2025). "For instance, in liver cancer, NAT10 stimulates the acetylation of the ACLY protein’s K468 site, which raises acetyl-CoA synthesis and triggers the transcription of drug-resistant genes, leading to chemotherapy resistance." (PMID 41310903, 2025). "In HCC, cell and animal experiments have demonstrated that the capacity of liver cancer cells to metastasize and evade apoptosis is increased by NAT10 under conditions of endoplasmic reticulum stress (ERS)." (PMID 41316475, 2025). "Intriguingly, elevated levels of ac4C and increased NAT10 expression have been observed in several human cancers, including colorectal and liver cancers." (PMID 40870000, 2025). "In order to investigate the effect of NAT10 on ERS status of liver cancer cells, siRNA-NAT10-1 (2710), siRNA-NAT10-2(3049), and SI-NC were established." (PMID 36765042, 2023). "Together, these findings strongly suggest that NAT10 represents an independent prognostic biomarker for liver cancer." (PMID 34094911, 2021). "This small molecule may serve as a valuable tool for further research into the role of NAT10 in liver cancer and potentially in other NAT10‐related diseases, marking a promising therapeutic strategy for HCC treatment." (PMID 41476650, 2025). "NAT10 promotes liver cancer metastasis and epirubicin chemoresistance by activating EMT." (PMID 39640362, 2024). "Second, high levels of NAT10 expression were shown to be almost consistently correlated with poor prognosis in liver cancer across gender, race, alcohol consumption, hepatitis virus, tumor stage, tumor grade and AJCC_T, with the highest HRs for poor OS and PFS." (PMID 34094911, 2021). "Therefore, NAT10 is likely to have an independent role in immune cell infiltration and could represent a unique prognostic biomarker in patients with liver cancers." (PMID 34094911, 2021).
liver cancer (continued). "Research has confirmed that the NAT10 and HSP90AA1 interaction has a regulatory effect on ERS-triggered metastasis and drug resistance in liver cancer cells." (PMID 41316475, 2025). "Among the liver cancer chemotherapeutic drugs oxaliplatin and doxorubicin, ACLY can be acetylated by NAT10 at lysine 468, which confers resistance to chemotherapy in HCC cells and mouse xenografts." (PMID 41316475, 2025). "Notably, literature evidence underscores the critical role of SMAD3 in liver cancer progression, prompting us to focus on SMAD3 as the key downstream target of NAT10 in subsequent investigations." (PMID 41476650, 2025). "While prior studies have suggested that NAT10 may promote HCC progression and drug resistance through RNA ac4C modification or independent pathways, these studies did not adequately address NAT10's critical role in the dynamic process of liver cancer development." (PMID 41476650, 2025).
Hutchinson-Gilford progeria syndrome (11 papers, 2014 to 2025). "N-acetyltransferase 10 (NAT10), an abundant nucleolar protein with both lysine and RNA cytidine acetyltransferase activities, has been implicated in Hutchinson-Gilford progeria syndrome and human cancer." (PMID 35986334, 2022). "NAT10 has also been implicated in the rapid cellular aging disease Hutchinson-Gilford progeria (HGP)." (PMID 34084768, 2021). "Inhibition of NAT10 can improve nuclear shape, repair DNA damage, and reverse cell proliferation defects, offering potential treatment for Hutchinson-Gilford progeria syndrome." (PMID 40779453, 2025). "NAT10 affected nuclear architecture in human laminopathies, including the premature-aging disease Hutchinson-Gilford progeria syndrome." (PMID 37612540, 2023). "It has been reported that NAT10 is a possible clinical target for a variety of progressive diseases, including cancer and Hutchinson-Gilford-Progeria syndrome (HGPS) 29,30." (PMID 37484809, 2023). "It has been found that a specific NAT10 inhibitor Remodelin could be used as a potential remedy for the Hutchinson-Gilford progeria syndrome." (PMID 38167491, 2024). "The enzyme, NAT10, is responsible for the incorporation of an acetyl moiety on the fourth position of cytidine and has been identified as a potential target for the treatment of diseases such as cancer, Hutchinson-Gilford Progeria Syndrome, and osteoporosis." (PMID 36736767, 2023). "In Hutchinson-Gilford Progeria Syndrome (HGPS), a premature aging disorder, NAT10 inhibition with the small molecule remodelin ameliorates nuclear defects and extends healthspan in mouse models by restoring chromatin organization and reducing DNA damage." (PMID 40588654, 2025).
melanoma (11 papers, 2017 to 2026). A malignant, usually aggressive tumor composed of atypical, neoplastic melanocytes. "Furthermore, NAT10 knockdown was found to suppress the expression of melanoma‐promoting genes, causing S‐phase arrest and reduced proliferation of melanoma cells." (PMID 39764566, 2025). "This phenotype was also observed in melanoma cell models, where Nat10-KO B16F10-OVA cells exhibited a milder suppression on CD8+ T cell cytotoxicity." (PMID 41542770, 2026). "NAT10 promotes malignant melanoma growth through MITF/cyclinD1/CDK2/p21-mediated cell cycle progression." (PMID 40588654, 2025). "used siRNA to inhibit NAT10 expression in human and mouse melanoma cells, resulting in S‐phase cell cycle arrest, with the mechanism involving NAT10 regulation of the p21/CDK2/cyclin D1 axis." (PMID 39764566, 2025). "In this study, we disclosed an important role of NAT10 in DTIC resistance of melanoma, mechanistically through promoting NAT10-mediated ac4C modification of DDX41 and ZNF746 mRNAs." (PMID 39246323, 2024). "Further, we elaborate that the role of NAT10 in promoting melanoma chemoresistance is attributed to its RNA acetyltransferase activity." (PMID 39246323, 2024). "Overall, these data coherently suggest that targeting NAT10 contributed to overcoming DTIC resistance of melanoma cells in vitro and in vivo." (PMID 39246323, 2024). "We measured mRNA acetylation levels in melanoma cells with either forcibly expressed NAT10 or vector control, and the ac4C level of mRNAs in the NAT10-OE cells was obviously increased." (PMID 39246323, 2024). "We measured the protein levels of DDX41 and ZNF746 in our established DR melanoma cells, revealing that increased NAT10 was correlated with elevated DDX41 and ZNF746 proteins." (PMID 39246323, 2024). "Our study elucidates the previously unrecognized role of NAT10-mediated ac4C modification in the chemoresistance of melanoma and provides a rationale for developing new strategies to overcome chemoresistance in melanoma patients." (PMID 39246323, 2024). "Meanwhile, the anti-melanoma effects induced by NAT10-knockout were also diminished in overexpressed DDX41 and ZNF746 levels in NAT10-KD cells." (PMID 39246323, 2024). "Collectively, these data strongly indicate that targeting NAT10 definitely benefits overcoming the DR of melanoma cells in vivo." (PMID 39246323, 2024). "To further evaluate the effects of NAT10 on melanoma tumor growth and DTIC sensitivity in vivo, we established a NAT10-KD or WT A375 cell-derived xenograft mouse model of melanoma in NOD/SCID mice and then treated it with DTIC or vehicle control every 3 days." (PMID 39246323, 2024). "We identified increased NAT10 expression in drug-resistant melanoma, which correlates with DTIC sensitivity in melanoma cell lines." (PMID 39246323, 2024). "In this study, we examined the expression of NAT10 in the DTIC-resistant melanoma cells and screened target genes of NAT10-mediated RNA modification using acetylated RNA immunoprecipitation and sequencing (acRIP-seq)." (PMID 39246323, 2024). "NAT10 was found to promote malignant melanoma progression by regulating the cell cycle and microphthalmia‐associated transcription factor, further underscoring its role in various malignancies." (PMID 39640362, 2024). "Analyzing tumor sizes after treatment, we observed that suppression of NAT10 in melanoma cells inhibited tumor growth and sensitized A375 cells to DTIC treatment." (PMID 39246323, 2024). "Collectively, these data suggest that DDX41 and ZNF746 are correlated with NAT10 expression and play a pivotal role in the treatment response and clinical outcomes of melanoma patients." (PMID 39246323, 2024). "Gain- and loss-of-function experiments in NAT10, or in DDX41 and ZNF746, altered the chemosensitivity of melanoma accordingly, and the two target genes also negatively correlated with clinical outcomes." (PMID 39246323, 2024).
melanoma (continued). "We detected mRNA acetylation levels in NAT10-OE A375 melanoma cells, and the acRIP-seq delineated the detailed mechanism of how NAT10 promoted melanoma drug resistance." (PMID 39246323, 2024). "To further determine the effects of NAT10 on drug resistance of melanoma cells, we inhibited the expression of NAT10 using short-hairpin RNA (shRNA) and selected shRNA #2 for subsequent experiments due to its highest knockdown efficacy." (PMID 39246323, 2024). "In the present study, we investigate the functional role of NAT10 in melanogenesis and melanoma growth." (PMID 28880216, 2017). "Using a small molecule or small interfering RNA targeting NAT10, we examined the effect of NAT10 inhibition on melanogenesis and melanoma growth in human and mouse melanoma cells." (PMID 28880216, 2017). "NAT10 promotes production of melanin and growth of melanoma." (PMID 39640362, 2024). "Intriguingly, ac4C peaks on DDX41 and ZNF746 of melanoma cells were abolished upon NAT10 knockdown." (PMID 39246323, 2024). "Nevertheless, whether NAT10 participates in the chemoresistance of melanoma cells remains to be clarified." (PMID 39246323, 2024). "Since NAT10 is an acetyltransferase, we investigated whether its promotion of melanoma cell chemoresistance is dependent on its acetyltransferase activity." (PMID 39246323, 2024). "This led us to hypothesize that NAT10 promotes melanoma malignancy by regulating ZF-C2H2 gene transcription." (PMID 39246323, 2024). "Finally, pharmacological inhibition of NAT10 with Remodelin sensitized melanoma cells to DTIC treatment in vitro and in a mouse xenograft model." (PMID 39246323, 2024). "Finally, we clarified the significance of targeting NAT10 in overcoming DTIC resistance of melanoma in vivo." (PMID 39246323, 2024). "In addition, NAT10 has aberrant expression in other malignant tumors undiscussed, such as melanoma, epithelial ovarian, and non-small cell lung cancers." (PMID 38233930, 2024). "To further clarify whether targeting NAT10 benefits overcoming melanoma chemoresistance, we evaluated a selective inhibitor of NAT10, Remodelin, in our previously established DR melanoma cells." (PMID 39246323, 2024). "NAT10 also has a potential role in increasing melanogenesis and melanoma growth." (PMID 34094911, 2021). "However, the effect of the pharmacological or genetic inhibition of NAT10 on cell cycle progression in human or mouse melanoma cells is questionable." (PMID 28880216, 2017). "Taken together, the presented data reveal that the inhibition of NAT10 by small molecules or genetic silencing suppresses melanin synthesis and melanoma growth by decreasing the expression of MITF and its target genes related to pigmentation and cell proliferation." (PMID 28880216, 2017). "In addition, NAT10 inhibition significantly increased cell cycle arrest in S-phase, thereby suppressing the growth and proliferation of malignant melanoma cells in vitro and in vivo." (PMID 28880216, 2017). "Genetic silencing or chemical inhibition of NAT10 resulted in diminished melanin synthesis through the suppression of melanogenesis-stimulating genes such as those encoding dopachrome tautomerase (DCT) and tyrosinase in B16F10 melanoma cells." (PMID 28880216, 2017). "We examined the anti-tumor growth effect of NAT10 inhibition in vivo to determine if NAT10 may promote melanoma growth through the regulation of cell cycle progression." (PMID 28880216, 2017). "To investigate this, we knocked down NAT10 expression in A2058 human malignant melanoma cells." (PMID 28880216, 2017). "Moreover, we show that the suppression of NAT10 reduces melanoma growth with abnormal expression of cell cycle-regulating genes such as CDK2 and cyclin D1 in vitro and in vivo." (PMID 28880216, 2017).
melanoma (continued). "Our results provide new clues to elucidate the biological function of NAT10 in differentiation and proliferation of melanocyte and melanoma and helpful information for the development of therapeutic strategy for treating skin diseases such as melanoma and hyperpigmentation disorders." (PMID 28880216, 2017). "However, the role of NAT10 in melanoma chemoresistance remains to be clarified." (PMID 39246323, 2024). "Furthermore, we investigated the mechanism of NAT10 promoting the mRNA ac4C modification of C2H2 zinc finger family members DDX41 and ZNF746 in chemoresistance of melanoma and finally evaluated the translational significance of NAT10 inhibitor in overcoming chemoresistance in vitro and in vivo." (PMID 39246323, 2024). "In addition, NAT10 expression is associated with melanoma progression patients, and a significant negative correlation of NAT10 with clinical outcomes is also revealed." (PMID 39246323, 2024). "In melanoma, NAT10 installs ac4C on DDX41 and ZNF746 transcripts to drive dacarbazine resistance; NAT10 inhibition (Remodelin) resensitized tumors in mice, nominating ac4C as a tractable axis." (PMID 41280938, 2025). "In melanogenesis and melanoma (SKCM), suppressing NAT10 inhibits the chemoresistance of melanoma by reducing the expression of the C2H2-ZF family members DDX41 and ZNF746, respectively." (PMID 41316475, 2025). "This prompted us to further examine the synergic efficacy of NAT10-specific inhibitor Remodelin and DTIC against melanoma." (PMID 39246323, 2024). "In addition, downstream targets of NAT10 could be used as potential biomarkers for melanoma malignancy before chemoresistance and metastasis, and the combination regimen could be considered for use in patients before disease progression, thus highlighting the translational value of our study." (PMID 39246323, 2024). "Remarkably, immunohistochemical staining for NAT10, DDX41, and ZNF746 protein on tumor tissues from melanoma patients showed that NAT10 had a positive correlation with these two proteins." (PMID 39246323, 2024). "To elucidate the effects of the pharmacological inhibition of NAT10 on melanin synthesis, we initially analyzed melanin contents in B16F10 mouse melanoma cells-treated with remodelin at different concentrations." (PMID 28880216, 2017). "However, the functional roles of NAT10 in melanoma growth remain unknown." (PMID 28880216, 2017). "Notably, our study clarifies the synergistic anti-melanoma effects of NAT10-specific inhibitor Remodelin with DTIC and sheds light on developing new strategies to improve treatment efficacy for melanoma patients." (PMID 39246323, 2024). "However, ectopic expression of NAT10 in MeWo and A375 cells remarkably augmented the resistance to DTIC treatment and abrogated DTIC-induced melanoma apoptosis, as evidenced by the increased IC50 value and decreased apoptosis rate." (PMID 39246323, 2024). "Here, we found that NAT10 knockdown induces cell cycle arrest and suppresses cell proliferation along with the expression of MITF and its target genes related to cell cycle progression in mouse and human melanoma cells." (PMID 28880216, 2017). "In summary, our data disclose the role of NAT10 in DTIC resistance of melanoma cells, elucidate the machinery through mediating ac4C modification of DDX41 and ZNF746 mRNAs, and shed light on developing new therapeutic strategies using Remodelin and DTIC for melanoma treatment." (PMID 39246323, 2024).
head and neck squamous cell carcinoma (10 papers, 2021 to 2025). A squamous cell carcinoma that arises from any of the following anatomic sites: lip and oral cavity, nasal cavity, paranasal sinuses, pharynx, larynx, and salivary glands. "Here, we demonstrated N-Acetyltransferase 10 (NAT10), as the only known “writer” of ac4C mRNA modification, was highly expressed in head and neck squamous cell carcinoma (HNSCC) patients with lymph node metastasis." (PMID 37914704, 2023). "In different datasets, high NAT10 expression was significantly correlated with poor prognosis in adrenocortical carcinoma, head and neck squamous cell carcinoma, liver hepatocellular carcinoma, kidney renal papillary cell carcinoma, and pheochromocytoma and paraganglioma." (PMID 34094911, 2021). "In head and neck squamous cell carcinoma (HNSCC), high NAT10 expression levels can predict poor patient prognosis." (PMID 39817252, 2025). "However, the outcomes of protein-protein interactions between NAT10 and its protein partners in head and neck squamous cell carcinoma (HNSCC) remain unexplored." (PMID 38246918, 2024). "Moreover, N-acetyltransferase 10 (NAT10), which plays a role in N4-acetylcytidine (ac4C) mRNA modification, promotes metastasis in head and neck squamous cell carcinoma and remodels the TME through the MAPK/ERK signaling pathway." (PMID 40176140, 2025). "Furthermore, in head and neck squamous cell carcinoma (HNSCC), NAT10-mediated ac4C modification of glycosylated lysosomal membrane protein (GLMP) mRNA activates the MAPK/ERK signaling pathway, leading to the promotion of lymph node metastasis." (PMID 41316475, 2025). "RNPS1 directly interacts with NAT10, inhibiting the ubiquitination degradation of NAT10 by E3 ubiquitin ligase, zinc finger SWIM domain-containing protein 6 (ZSWIM6), thereby promoting translation process of genes regulating malignant progression in head and neck squamous cell carcinoma." (PMID 40588654, 2025).